GFAP (glial fibrillary acidic protein)
Diseases named in the same sentence as GFAP in open-access papers (continued):
Sharing a sentence is not in itself a finding about the gene and the disease.
Stroke (continued). "As we have already shown, this study provides compelling evidence supporting the diagnostic utility of serum GFAP and UCH-L1 in the acute evaluation of patients with suspected stroke." (PMID 40649119, 2025). "Among brain-enriched proteins, glial fibrillary acidic protein (GFAP) and s-100b calcium binding protein are the most used, as they increase early after stroke and are associated with extent of brain injury and the degree of disability." (PMID 40863995, 2025). "Although prior, and ongoing, study of the LVOne GFAP LFT has focussed on LVO stroke, GFAP is a biomarker of considerable promise in TBI." (PMID 40650780, 2025). "PHA treatment also reduced CD68+/SYP+ on both sides of the hippocampi (p<0.001) and GFAP+/SYP+ cells in the hippocampi ipsilateral to stroke injury (p<0.001)." (PMID 40661422, 2025). "Immunohistochemical examinations of the post-stroke hippocampal brain sections revealed increased Iba-1-positive microglia cells and GFAP-positive astrocytes." (PMID 41369361, 2025). "As a neuroinflammatory marker, GFAP has also been used to assess the extent of brain damage in cases of stroke or neurodegenerative conditions." (PMID 41296388, 2025). "In the present work, we aimed to delineate the effects of mono- and combinatorial pre-treatment upon neurological status and neurological integrity biomarkers, namely protein S100b, GFAP, procalcitonin, and galectin-3, following a cerebrovascular accident." (PMID 40863995, 2025). "Our research indicates that GFAP is an exceptionally reliable biomarker for differentiating acute stroke from stroke mimics, demonstrating outstanding sensitivity, perfect specificity, and robust positive and negative predictive values." (PMID 40649119, 2025). "This systematic review explored the association between prediabetes and stroke through significant biomarkers like IL-6, D-dimer, NSE and GFAP." (PMID 41150802, 2025). "GFAP levels were similar in the hippocampi of young and old stroke mice, on the ipsilateral and contralateral sides of stroke injury." (PMID 40661422, 2025). "When the CNS is damaged, such as through stroke, dementia, or brain injury, astrocytes are transformed into reactive astrocytes, such as in hypertrophy and hyperplasia, and GFAP is used to label these reactive astrocytes." (PMID 40725403, 2025). "For example, in stroke care, blood-based biomarkers including GFAP and NfL are used to assess injury severity and guide treatment decisions." (PMID 41465199, 2025). "In individuals with prediabetes or T2DM, elevated levels of GFAP and NSE can indicate early neuronal damage, providing insight into the risk of cerebrovascular events, including stroke." (PMID 41296388, 2025). "Glial fibrillary acidic protein in serum is a potential stroke biomarker, and changes in its concentration can be used for monitoring stroke patients." (PMID 40862948, 2025). "GFAP is a significant classifier (p < 0.001) of stroke, with a sensitivity of 94.2%, specificity of 100%, positive predictive value of 100%, negative predictive value of 80%, and accuracy of 95.3%." (PMID 40649119, 2025). "In this rat MCAO‐like model, the neural tissue further deteriorated until 60 days after the stroke, when cavities form and the adjacent GFAP signal decreased compared with that 30 days after the stroke." (PMID 40401537, 2025). "The temporal dynamics of GFAP release make it particularly useful for early differentiation between stroke subtypes, which is critical for guiding appropriate therapeutic interventions." (PMID 40026944, 2025). "N-terminal pro B-type natriuretic peptide (NT-proBNP) is increased in the early phase after ICH, and its combination with glial fibrillary acidic protein (GFAP) is useful for differentiating stroke subtypes in the hyperacute phase." (PMID 40933575, 2025). "In one biracial cohort, individuals with diabetes had lower GFAP levels, those with history of stroke had higher NfL, and those with chronic kidney disease had higher NfL and lower P-tau181." (PMID 40107919, 2025).
Stroke (continued). "Since reactive astrocytes have also been shown to affect remyelination after experimental stroke, we next evaluated the spatiotemporal distribution of these glial cells in human ischaemic lesions using the GFAP marker." (PMID 39703181, 2025). "Overall, the findings support the clinical applicability of serum GFAP and, to a lesser extent, UCH-L1 as valuable diagnostic tools for the early and accurate classification of stroke type." (PMID 40649119, 2025). "Remarkably, it was found that glial fibrillary acidic protein (GFAP) was sensitive in differentiating IS from hemorrhagic stroke at 3 h and 24 h after stroke onset." (PMID 40362186, 2025). "There were also more GFAP+ astrocytes in the peri-atrophic region of old stroke mice than young stroke mice (p=0.049); more GFAP+ astrocytes in the ipsilateral hippocampi of old stroke mice than young stroke mice (p =0.037)." (PMID 40661422, 2025). "This correlation has demonstrated good sensitivity and specificity, particularly in cases involving larger hematomas, making GFAP a promising indicator for stroke differentiation in clinical diagnostics." (PMID 40136933, 2025). "Both GFAP and S100B serve as promising biomarkers for assessing the severity and prognosis of stroke." (PMID 40863995, 2025). "There is a strong correlation between GFAP blood levels and hematoma size, with significantly elevated concentrations observed in HS compared to IS during the first 24 h after stroke onset." (PMID 40136933, 2025). "To investigate TT1Ct effects on the glial subpopulation in stroke, we first evaluated GFAP and complement component 3 (C3) co-staining after 5 h or 24 h of injury." (PMID 40225562, 2025). "This supports the relevance of GFAP as a biomarker in assessing brain injury and differentiating between stroke types, highlighting its significance in individuals with diabetes at risk for cerebrovascular events." (PMID 41296388, 2025). "Compared to our previous work at the acute phase of stroke (3 days post-ischemia), our results on GFAP staining at the subacute phase (7 days) demonstrate that reactive gliosis is maintained in db/db mice." (PMID 39816479, 2025). "One promising biomarker for differentiating between stroke types is Glial Fibrillary Acidic Protein (GFAP)." (PMID 40136933, 2025). "For example, D-dimer, GFAP, and 8-iso-prostaglandin F2α (8-iso-PGF2α) can be detected within minutes to 3 h of a stroke." (PMID 40949500, 2025). "Glial fibrillary acidic protein (GFAP), D-dimer, and neuron-specific enolase (NSE) are diagnostic markers that can already subtype stroke and estimate lesion burden." (PMID 40949500, 2025). "Immunohistochemistry at day 10 post-stroke showed robust GFAP+ glial scar formation surrounding the lesion cavity." (PMID 40631280, 2025). "While there are several other markers of brain injury, this study demonstrated that S100B, GFAP and NSE have potential for use as biomarkers in the development of prediabetes-associated stroke events." (PMID 41296388, 2025). "Our analysis outlined an attenuation of overall astrogliosis translated by a reduced GFAP+ reactivity at the injury site in VEGF‐E‐treated mice 4 days after stroke." (PMID 40277075, 2025). "GFAP typically increases after stroke, reaching peak levels 48 h after stroke as a result of neural damage." (PMID 41306424, 2025). "Changes in GFAP expression serve as an indicator of the extent of pathological damage in brain tissue following stroke." (PMID 40790939, 2025). "D-dimer and GFAP were each reported in separate single studies, both showing significant elevations in hyperglycaemic individuals with stroke or neurocognitive impairment." (PMID 41150802, 2025). "This temporal and quantitative difference makes GFAP a valuable biomarker for distinguishing between stroke types, particularly in the early stages of stroke biological events." (PMID 40136933, 2025). "We aimed to evaluate GFAP in serum as predictor of post-stroke cognitive impairment (PSCI) at 90 days." (PMID 40421099, 2025).
Stroke (continued). "While focused on GFAP and cognitive impairments, GFAP is also considered an important marker in stroke assessment." (PMID 41296388, 2025). "Our data reveal a significant correlation between serum levels of NfL and GFAP and functional outcomes 3 months after index stroke." (PMID 38400734, 2024). "Prediction of functional outcome after severe acute ischemic stroke was improved by the blood-based biomarkers serum NfL and GFAP, measured in the acute phase of stroke." (PMID 38400734, 2024). "Glial fibrillary acidic protein (GFAP), an astrocytic protein found almost exclusively in the brain, is a promising biomarker of brain tissue damage in neurological conditions, including stroke." (PMID 39777311, 2024). "In TBI, as well as in stroke and neurodegenerative models, GFAP expression is increased chronically at the lesion core and this delimits tissue recovery and repopulation by new axons." (PMID 39683446, 2024). "In recent years, growing evidence supports measurement of GFAP in cerebrospinal fluid or serum as a biomarker for diagnosis and prognosis of neurodegenerative diseases, stroke and TBI." (PMID 37702572, 2024). "Increased GFAP density was also found 1 month after experimental stroke induction in the sensorimotor cortex and dorsolateral striatum of mice." (PMID 38674304, 2024). "The aim of the present review, therefore, is to analyze and summarize the recent relevant clinical literature on molecular markers of focal hypoxia with particular emphasis on the prognostic role of S100B protein and the GFAP in patients with stroke." (PMID 39459548, 2024). "Post-mortem studies also show a strong correlation between serum GFAP levels and the severity of brain injury, highlighting its diagnostic utility in assessing TBI and stroke outcomes." (PMID 39796043, 2024). "Stroke subtypes can be differentiated using both biomarkers, and a biomarker panel including GFAP and UCH-L1 enhances sensitivity and specificity." (PMID 39459548, 2024). "In the context of traumatic brain injury (TBI) and stroke, GFAP has emerged as a key biomarker indicating astrocytic damage and reactivity." (PMID 39796043, 2024). "We found significant correlations between functional outcome 3 months after the index stroke and serum biomarker levels of NfL [p < 0.0001; r = 0.47 (95% CI: 0.36–0.58)] and GFAP [p < 0.0001; r = 0.48 (95% CI: 0.37–0.58)]." (PMID 38400734, 2024). "Elevated blood GFAP and NfL levels can be observed in other neurodegenerative diseases (e.g., Parkinson’s disease, amyotrophic lateral sclerosis), stroke, or traumatic brain injury." (PMID 39125924, 2024). "The integration of S100B and GFAP with existing clinical scales can improve the accuracy and predictive power in assessing stroke outcomes." (PMID 39459548, 2024). "At the time when functional recovery was observed, the NPCs in the stroke-injured cortex had differentiated primarily into GFAP+ astrocytes." (PMID 38339065, 2024). "While plenty of studies characterize serum GFAP levels as a potential biomarker in predicting stroke severity and outcome, to the best of our knowledge, this is one of the first papers characterizing ADEVs’ protein cargo in stroke patients." (PMID 38891912, 2024). "Elevated serum GFAP within 24 h predicts poor functional outcomes independently at one-year post-stroke follow-up." (PMID 38891912, 2024). "Conversely, biomarkers like GFAP show promise in distinguishing stroke subtypes, predicting hemorrhagic transformation and aids in distinguishing between hemorrhagic and ischemic strokes based on the extent of blood-brain barrier disruption." (PMID 39459548, 2024). "Next, to assess the temporal profile of post-stroke EV GFAP levels, we measured full-length GFAP band intensities in TEV and ADEV samples collected longitudinally at D1, D7, and M1." (PMID 38891912, 2024).
Stroke (continued). "Data have shown that serum GFAP levels increase with neurological deficit and lesion size, reflect the severity of the stroke, and improve the ability of the National Institutes of Health Stroke Scale (NIHSS) score to predict poor functional outcomes." (PMID 38891912, 2024). "It was previously related that serum GFAP levels improve the ability of the NIHSS score to predict poor stroke outcomes." (PMID 38891912, 2024). "This circumstance makes it more challenging to differentiate between the amount of elevation of serum NfL/GFAP induced by the comorbidities and by minor stroke." (PMID 38400734, 2024). "Meanwhile, it was shown that AEVs derived from OGD astrocytes suppressed GFAP expression in astrocytes and increased neurite outgrowth after stroke." (PMID 37676390, 2024). "Reactive astrocytes (GFAP+)in SBE-LucRT mice to measure TGFβ signaling after stroke by occlusion of a distal middle cerebral artery." (PMID 38891053, 2024). "More precisely, evidence from studies on traumatic brain injury and stroke show increasing GFAP blood levels already few hours after the corresponding damage, thus suggesting GFAP release due to damaged astrocytes." (PMID 38536455, 2024). "Due to its exclusive production by astrocytes, GFAP is uniquely located in the brain and demonstrates prognostic role in patients with stroke." (PMID 39459548, 2024). "-Circulating microRNAs and proteins perform equally well in the diagnosis of ischemic stroke-GFAP differentiated subtypes of stroke-A biomarker panel of GFAP and UCH-L1 improved the sensitivity and specificity of UCH-L1 alone to differentiate stroke." (PMID 39459548, 2024). "The reaction of astrocytes to remote ischemia in the hippocampus are consistent: the GFAP levels and the numbers of GFAP-positive (GFAP+) cells increase shortly after the stroke and remain elevated for several months." (PMID 38504666, 2024). "Here, we found that stroke significantly decreased the expression of GFAP and Cx43 in the bilateral hippocampus, but EE increased GFAP/Cx43 expression." (PMID 37752881, 2024). "GFAP levels are found to be positively correlated with stroke outcome, infarct volume, and NIHSS scores in patients with AIS." (PMID 39459548, 2024). "An equally interesting fact is that GFAP levels in the CSF make it possible to distinguish between patients with IS and healthy people within the first 24 h after trauma, and that GFAP correlates with the severity of stroke." (PMID 39001884, 2024). "A recent study also reported a positive correlation between serum GFAP level and the National Institutes of Health Stroke Scale (NIHSS) score in acute IS." (PMID 39595521, 2024). "The reviewed studies highlight the potential of S100B and GFAP as significant biomarkers in the prognosis and diagnosis of patients with stroke and their ability of predicting long-term neurological deficits." (PMID 39459548, 2024). "GFAP (Glial fibrillary acidic protein): A protein found in the cells that support brain neurons, GFAP levels can be used to detect stroke and other brain injuries." (PMID 40777969, 2024). "When comparing the relationship between the IS group and SM group and the severity of a stroke, we found that IS patients had significantly higher serum GFAP, NFL, OCLN, Claudin-5, and ZO-1 levels in both groups as compared to SMs." (PMID 39595521, 2024). "A recent study of GFAP acquisition in the early phase of stroke onset also observed that blood GFAP levels increases with time." (PMID 39777311, 2024). "Several lines of evidence support that in response to stroke, astrocytes convert to a reactive phenotype chiefly characterized by up‐regulation of GFAP and cellular hypertrophy." (PMID 36794521, 2023). "Studies of stroke, spinal cord injury, and impaired neurogenesis have suggested that ependymal cells are replaced by GFAP+ astrocytes as a form of gliotic scarring." (PMID 37620636, 2023).
Stroke (continued). "GFAP and D-dimer measured with ELISA have been combined with symptom-based stroke scales for LVO identification." (PMID 36604741, 2023). "In patients with symptoms lasting up to 4.5 h, we used GFAP to identify ICrH and PreSS to identify stroke and LVO." (PMID 36604741, 2023). "The stroke cavity is walled off by glial scar tissues; hence it can be traced by using GFAP and/or S100β staining." (PMID 37867250, 2023). "We aimed to determine the performance of glial fibrillary acidic protein (GFAP) independently and in combination with the Prehospital Stroke Score (PreSS) for identification and differentiation of acute stroke within 4.5 h after symptom onset." (PMID 36604741, 2023). "Glial scar formation as indicated by means of assessing the mean fluorescence intensity of GFAP revealed an ever-increasing GFAP intensity over time after stroke induction." (PMID 37554272, 2023). "Up-regulation of S100B protein synthesis and leakage of S100B from damaged astrocytes that express GFAP in the glial scar can be induced by acute brain injury (e.g., stroke or TBI)." (PMID 36986535, 2023). "This implies that astrocyte activation is essential for protecting brain tissue in stroke and that GFAP plays a role in this process, especially in the cell resistance to oxidative stress (De Pabloet al., 2013)." (PMID 39816762, 2023). "GFAP is mainly expressed in the astrocytes of the CNS and is relatively frequently used in the study of various diseases, such as traumatic brain injury, stroke and brain tumour." (PMID 37239252, 2023). "Because nerve damage activates astrocytes and rapidly elevates GFAP production, GFAP levels are utilized as markers of neurological damage in trauma and stroke." (PMID 36782340, 2023). "In contrast, astrocytic reactivity at 7 DPI was reduced in the group exposed to both preconditioning and stroke, as indicated by GFAP immunoreactivity." (PMID 37658339, 2023). "It is worth noting that GFAP concentrations reported in the literature exhibit considerable variation, influenced by factors such as the time elapsed after the stroke episode and the race of the patients." (PMID 38032374, 2023). "Serum GFAP concentrations have been reported to be increased with the highest values at 48 h after stroke onset and remains elevated for at least 5 days after stroke." (PMID 37342100, 2023). "Ependymal cells expressed robust levels of GFAP in the brain ipsilateral to the lesion and exhibited the phenotype and morphology of radial glia and reactive astrocytes at 7 and 14 days after stroke." (PMID 37008045, 2023). "GFAP and NT-proBNP levels were validated as informative blood biomarkers in the differentiation of IS and HS and using a combination of GFAP and NT-proBNP is suggested as a feasible strategy to differentiate stroke subtypes in the hyperacute phase of stroke." (PMID 37685295, 2023). "In conclusion, our study confirms the role of GFAP and NT-proBNP in the differentiation of IS and HS during the hyperacute stage of stroke." (PMID 37685295, 2023). "We used GFAP-TK mice to selectively ablate neural stem cells prior to stroke following an established ganciclovir (GCV) administration paradigm." (PMID 37816732, 2023). "To assess astrocyte cytoskeletal structure, we immunohistostained for GFAP in the peri-infarct area during the acute (24 h) and subacute (7 days) phases following dMCAO, and the chronic (30 days) phase after photothrombotic stroke." (PMID 38240014, 2023). "Mice subjected to a photothrombosis model of stroke, demonstrated a delay/impairment in neurological restoration in GFAP-/-Vim-/- mice indicating the importance of GFAP and vimentin in functional recovery and axonal remodeling following stroke." (PMID 38464735, 2023). "In ischemic stroke patients, RBP4 > 48.75 lg/mL and GFAP < 0.07 ng/mL were found to be independent predictors of stroke subtypes after a multivariate logistic regression analysis." (PMID 37892701, 2023).